ARFGEF2 (ARF guanine nucleotide exchange factor 2)
Description:
Promotes guanine-nucleotide exchange on ARF1 and ARF3 and to a lower extent on ARF5 and ARF6. Promotes the activation of ARF1/ARF5/ARF6 through replacement of GDP with GTP. Involved in the regulation of Golgi vesicular transport. Required for the integrity of the endosomal compartment. Involved in trafficking from the trans-Golgi network (TGN) to endosomes and is required for membrane association of the AP-1 complex and GGA1. Seems to be involved in recycling of the transferrin receptor from recycling endosomes to the plasma membrane. Probably is involved in the exit of GABA(A) receptors from the endoplasmic reticulum. Involved in constitutive release of tumor necrosis factor receptor 1 via exosome-like vesicles; the function seems to involve PKA and specifically PRKAR2B. Proposed to act as A kinase-anchoring protein (AKAP) and may mediate crosstalk between Arf and PKA pathways.
Synonyms: BIG2; PVNH2; dJ1164I10.1
Tractability: PROTAC: ubiquitination databases record sites on it; its protein half-life has been measured.
Gene: Protein-coding gene on chromosome 20 (48,921,711 to 49,036,693, forward strand). Ensembl gene ENSG00000124198.
Subcellular location: Cytoplasm; Membrane; Golgi apparatus; Cytoplasm, perinuclear region; Golgi apparatus, trans-Golgi network; Endosome; Cytoplasm, cytoskeleton, microtubule organizing center, centrosome; Cell projection, dendrite; Cytoplasmic vesicle; Synapse; Cytoplasm, cytoskeleton
Subcellular location (Human Protein Atlas): Golgi apparatus
Pathways (Reactome):
Metabolism of proteins: Association of TriC/CCT with target proteins during biosynthesis
Gene Ontology:
Molecular function: guanyl-nucleotide exchange factor activity; protein binding; protein kinase A regulatory subunit binding; GABA receptor binding; myosin binding
Biological process: endomembrane system organization; endosome organization; Golgi to plasma membrane transport; intracellular signal transduction; positive regulation of tumor necrosis factor production; receptor recycling; exocytosis; regulation of ARF protein signal transduction
Cellular component: cytosol; Golgi apparatus; Golgi membrane; membrane; microtubule organizing center; recycling endosome; asymmetric synapse; axonemal microtubule; cytoplasmic vesicle; dendritic spine; symmetric synapse; trans-Golgi network; centrosome; cytoplasm; cytoskeleton; dendrite; endosome; GABA-ergic synapse; glutamatergic synapse; perinuclear region of cytoplasm; postsynapse; presynapse; synapse
Genetic constraint (gnomAD): Loss-of-function variants: 72 observed, 224.07 expected, observed/expected ratio (o/e) 0.32, 90% interval 0.26 to 0.39. The upper end of that interval is the gene's LOEUF score, 0.39, which puts it in group 1 of 6, group 1 being the genes least tolerant of losing a copy. Missense variants: 1,741 observed, 2,316.7 expected, observed/expected ratio (o/e) 0.75, 90% interval 0.72 to 0.78. Synonymous variants: 732 observed, 838.23 expected, observed/expected ratio (o/e) 0.87, 90% interval 0.82 to 0.93.
Gene-disease validity (ClinGen):
ClinGen rates the evidence that ARFGEF2 causes each of these diseases.
periventricular heterotopia with microcephaly, autosomal recessive (autosomal recessive): Definitive.
Homologues: Orthologues: chimpanzee ARFGEF2 (99% identical), macaque ARFGEF2 (99% identical), dog ARFGEF2 (98% identical), guinea pig ARFGEF2 (97% identical), pig ARFGEF2 (97% identical), rabbit ARFGEF2 (96% identical), mouse Arfgef2 (96% identical), rat Arfgef2 (95% identical), tropical clawed frog arfgef2 (81% identical), zebrafish arfgef2 (79% identical), Drosophila melanogaster Sec71 (59% identical), Caenorhabditis elegans agef-1 (42% identical), and 4 more. Paralogues in human: ARFGEF1 (77% identical), GBF1 (20% identical), IQSEC1 (12% identical), IQSEC2 (11% identical), MON2 (11% identical), CYTH3 (10% identical), CYTH1 (10% identical), IQSEC3 (10% identical), CYTH2 (10% identical), CYTH4 (10% identical), PSD3 (7% identical), PSD (7% identical), and 3 more.
Diseases named in the same sentence as ARFGEF2 in open-access papers:
ARFGEF2 is named in the same sentence as 28 diseases in open-access papers, as found by Europe PMC text mining. Sharing a sentence is not in itself a finding about the gene and the disease. The quoted sentences say what the papers report.
microcephaly (12 papers, 2012 to 2026). A congenital or acquired developmental disorder in which the circumference of the head is smaller than normal for the person's age and sex. "Pathogenic mutations in the ARFGEF2 gene are associated with autosomal recessive periventricular nodular heterotopia with microcephaly (ARPHM)." (PMID 42255913, 2026). "A mutation in ARFGEF2 has been previously associated with several phenotypes related to brain development, including microcephaly." (PMID 35659227, 2022). "A second form of autosomal recessive PH with microcephaly (ARPHM) has been associated with mutations in the ARFGEF2 gene." (PMID 25883548, 2015). "This case highlights progressive microcephaly as a key distinguishing feature of ARFGEF2-related PVNH and underscores the importance of early genetic diagnosis to guide targeted surveillance for extra-CNS complications and multidisciplinary care." (PMID 42200925, 2026). "Among recessive forms, ARFGEF2-related disorder is uniquely characterised by the association of diffuse PVNH and progressive microcephaly." (PMID 42200925, 2026). "For instance, microcephaly has been associated with mutations in RAB3GAP/RAB18, ARFGEF2, ARF1, kinesin KIF2A, or dynein heavy chain, all affecting both membrane trafficking and neuronal morphogenesis." (PMID 39115595, 2024). "Lastly, mutations in the human genes for ARFGEF2 and ARF1 have been associated with cortical malformations, including periventricular nodular heterotopia and microcephaly, indicating that the ARFGEF2-Arf1 pathway is critical for cerebral cortical development." (PMID 37848288, 2023). "Some patients affected by microcephaly and periventricular heterotopia present mutations in the ARFGEF2 (ADP-ribosylation factor guanine nucleotide-exchange factor-2), encoding for BIG2 [brefeldin A (BFA)-inhibited GEF2 protein]." (PMID 35069108, 2021). "BIG1 cannot compensate for lack of BIG2 function in mammals, as mutations in BIG2 lead to the neurological disease microcephaly with periventricular heterotopia in humans and deletion of the mouse BIG2 (Arfgef2) gene causes early embryonic lethality." (PMID 23386609, 2013). "Another example has been reported by Sheen and colleagues who identified loss-of-functions mutations in the ADP-ribosylation Factor Guanine Exchange Factor 2 (ARFGEF2) in patients with an autosomal recessive periventricular heterotopia with microcephaly (ARPHM; MIM #608097)." (PMID 31832602, 2019).
Periventricular heterotopia (6 papers, 2016 to 2026). A form of gray matter heterotopia were the mislocalized gray matter is typically located periventricularly, also sometimes called subependymal heterotopia. "Concerning the roles of Arfs in cortical development, mutations in human genes for ARF1 and its GEF, ARFGEF2, have been linked to periventricular nodular heterotopia, suggesting the involvement of Arf1 in cortical radial migration." (PMID 37848288, 2023). "In addition, no variants were observed in the known or possible genes for periventricular heterotopia including FLNA, ARFGEF2 and ERMARD, nor were pathogenic variants seen in other known genes implicated for brain malformation syndromes, intellectual disability or ADHD conditions." (PMID 28868155, 2016).
epilepsy (3 papers, 2015 to 2020). A brain disorder characterized by episodes of abnormally increased neuronal discharge resulting in transient episodes of sensory or motor neurological dysfunction, or psychic dysfunction. "Genes implicated in primary microcephaly with associated features such as cognitive and motor impairment and epilepsy includeSLC25A19,ATR,ARFGEF2, andRAB3GAP119." (PMID 26535115, 2015).
Intellectual disability (3 papers, 2016 to 2020). "Some studies have shown that ARFGEF2 mutations can lead to severe intellectual disability and are closely related to neuronal migration disorders." (PMID 32655475, 2020).
autosomal recessive periventricular heterotopia (2 papers, 2022 to 2023). "For instance, mutations in the ARFGEF2 gene, responsible for encoding the BIG2 protein and identified in patients with autosomal recessive periventricular heterotopia with microcephaly, are closely associated with neuronal migration disorders." (PMID 38250258, 2023).
developmental delay (2 papers, 2021 to 2022). "Additionally, ARFGEF2, MIPEP, NONO, SH2B1, and TMEM70 led to LVNC complicating developmental delay." (PMID 34819141, 2021).
breast carcinoma (1 paper, 2022). "ARFGEF2:SULF2 fusion was also called for MCF-7 cell line and SLC27A6:ADAMTS19 was previously identified in breast cancer with short reads." (PMID 35164688, 2022).
cystic fibrosis (1 paper, 2019). Autosomal recessive disorder caused by pathogenic variants in the CFTR gene (cystic fibrosis transmembrane conductance regulator), which encodes a chloride and bicarbonate channel expressed in epithelial cells, and follow the diagnosis criteria. "SNPs in the VCAM-1 and ARFGEF2 genes, a deletion in the CTFR gene and CNVs in the HLA gene were found to be associated with cases of sickle cell anaemia, cystic fibrosis and rheumatoid arthritis, respectively." (PMID 30084865, 2019).
subependymal nodular heterotopia (1 paper, 2022). "Subependymal nodular heterotopias have been described in patients with chromosomal rearrangements, as well as associated with intragenic gene mutations (e.g., in FLNA, ARFGEF2, DCHS1, FAT4, ERMARD, and NEDD4L)." (PMID 35585091, 2022).
neurodevelopmental disorder (2 papers, 2022 to 2026). A behavioral and cognitive disorder with onset during the developmental period that involves impaired or aberrant development of intellectual, motor, or social functions. "Some upstream regulators of ARF GTPases, such as the two GEFs, ARFGEF1 (BIG1) and ARFGEF2 (BIG2), have also been implicated in neurodevelopmental disorders." (PMID 41381732, 2026).
neurologic disease (2 papers, 2016). "These TGN-localized Arf-GEFs are universally conserved in eukaryotes, and their importance is underscored by neurological disorders associated with mutations in the BIG2/ARFGEF2 gene." (PMID 26765562, 2016).
cancer (1 paper, 2021). A tumor composed of atypical neoplastic, often pleomorphic cells that invade other tissues. "The oncogenic actions of ARFGEF2 remain unclear not only in PC but also tumorigenesis in general with n = 4 articles in PubMed under “ARFGEF2 and Cancer”." (PMID 33578925, 2021).
tumor (1 paper, 2021). "In both TCGA PanCancer and MSKCC cohorts, ARFGEF2 downregulations increased the risk of PC relapse and this biomarker value is independent of age at diagnosis, tumor stage, WHO PC grade, and surgical margin status." (PMID 33578925, 2021).
ARFGEF2 also shares sentences with these, for which no sentence is quoted: bipolar disorder (2 papers); neuronal migration disorders (2); post-traumatic stress disorder (2); Ciliopathies (1); Down syndrome (1); dyslexia (1); Failure to thrive (1); Huntington disease (1); infection (1); lupus (1); Obesity (1); Primary microcephaly (1); schizophrenia (1); tuberous sclerosis (1); West syndrome (1).